KRTAP1-5 (keratin associated protein 1-5)
Description:
In the hair cortex, hair keratin intermediate filaments are embedded in an interfilamentous matrix, consisting of hair keratin-associated proteins (KRTAP), which are essential for the formation of a rigid and resistant hair shaft through their extensive disulfide bond cross-linking with abundant cysteine residues of hair keratins. The matrix proteins include the high-sulfur and high-glycine-tyrosine keratins.
Synonyms: KAP1.5; KRTAP1.5
Tractability: No criterion of Open Targets' tractability assessment is met for any kind of drug.
Gene: Protein-coding gene on chromosome 17 (41,026,026 to 41,027,208, reverse strand). Ensembl gene ENSG00000221852.
Pathways (Reactome):
Developmental Biology: Keratinization
Gene Ontology:
Molecular function: protein binding
Cellular component: cytosol; keratin filament
Genetic constraint (gnomAD): Loss-of-function variants: 10 observed, 15.39 expected, observed/expected ratio (o/e) 0.65, 90% interval 0.4 to 1.1. The synonymous counts are far from expectation, so gnomAD's model fits this gene poorly and the ratio says little. Missense variants: 234 observed, 226.42 expected, observed/expected ratio (o/e) 1.03, 90% interval 0.93 to 1.15. Synonymous variants: 107 observed, 79.61 expected, observed/expected ratio (o/e) 1.34, 90% interval 1.15 to 1.58.
Homologues: Orthologues: macaque KRTAP1-5 (93% identical), chimpanzee KRTAP1-5 (92% identical), mouse Krtap1-5 (43% identical), rat Krtap1-5 (43% identical). Paralogues in human: KRTAP1-3 (88% identical), KRTAP1-1 (86% identical), KRTAP1-4 (59% identical), KRTAP4-12 (38% identical), KRTAP4-6 (37% identical), KRTAP4-11 (36% identical), KRTAP4-3 (36% identical), KRTAP4-9 (36% identical), KRTAP4-5 (34% identical), KRTAP9-1 (34% identical), KRTAP9-2 (34% identical), KRTAP9-6 (34% identical), and 35 more.